DNMBP (dynamin binding protein)
Description:
Plays a critical role as a guanine nucleotide exchange factor (GEF) for CDC42 in several intracellular processes associated with the actin and microtubule cytoskeleton. Regulates the structure of apical junctions through F-actin organization in epithelial cells. Participates in the normal lumenogenesis of epithelial cell cysts by regulating spindle orientation. Plays a role in ciliogenesis (By similarity). May play a role in membrane trafficking between the cell surface and the Golgi (By similarity).
Synonyms: ARHGEF36; KIAA1010; TUBA; CTRCT48
Tractability: PROTAC: ubiquitination databases record sites on it.
Gene: Protein-coding gene on chromosome 10 (99,875,577 to 100,009,947, reverse strand). Ensembl gene ENSG00000107554.
Subcellular location: Cytoplasm; Golgi apparatus, Golgi stack; Cytoplasm, cytoskeleton; Synapse; Cell junction
Subcellular location (Human Protein Atlas): Cytosol; Golgi apparatus; Nucleoli; Nuclear bodies; Nucleoplasm
Pathways (Reactome):
Signal Transduction: CDC42 GTPase cycle
Gene Ontology:
Molecular function: guanyl-nucleotide exchange factor activity; protein binding
Biological process: regulation of cell shape; cilium assembly; regulation of small GTPase mediated signal transduction; intracellular signal transduction
Cellular component: anchoring junction; cell-cell junction; cytoplasm; cytosol; Golgi apparatus; presynapse; synapse; cytoskeleton; Golgi stack
Genetic constraint (gnomAD): Loss-of-function variants: 84 observed, 151.75 expected, observed/expected ratio (o/e) 0.55, 90% interval 0.46 to 0.66. The upper end of that interval is the gene's LOEUF score, 0.66, which puts it in group 2 of 6, group 1 being the genes least tolerant of losing a copy. Missense variants: 1,747 observed, 2,017.1 expected, observed/expected ratio (o/e) 0.87, 90% interval 0.83 to 0.9. Synonymous variants: 702 observed, 780.57 expected, observed/expected ratio (o/e) 0.9, 90% interval 0.84 to 0.96.
Homologues: Orthologues: chimpanzee DNMBP (99% identical), macaque DNMBP (96% identical), dog DNMBP (83% identical), pig DNMBP (83% identical), rabbit DNMBP (82% identical), guinea pig DNMBP (81% identical), mouse Dnmbp (76% identical), rat Dnmbp (75% identical), tropical clawed frog dnmbp (55% identical), zebrafish dnmbp (50% identical), Caenorhabditis elegans dnbp-1 (18% identical). Paralogues in human: ARHGEF38 (20% identical), ARHGEF37 (13% identical).
Diseases named in the same sentence as DNMBP in open-access papers:
DNMBP is named in the same sentence as 35 diseases in open-access papers, as found by Europe PMC text mining. Sharing a sentence is not in itself a finding about the gene and the disease. The quoted sentences say what the papers report.
cataract (2 papers, 2021 to 2024). Partial or complete opacity of the crystalline lens of one or both eyes that decreases visual acuity and eventually results in blindness. "IAA downregulated still-life protein (sif), orthologous to human dynamin binding protein involved in cataracts, regulating synaptic differentiation through the organization of the actin cytoskeleton by activating Rho-like GTPases78,79." (PMID 38594449, 2024).
tumor (5 papers, 2017 to 2025). "Additionally, DNMBP, which supports epithelial structure by regulating apical junctions, is consistently down-regulated at the protein level across human tumor types (the Human Protein Atlas)." (PMID 41468516, 2025). "In addition, genes related to tumor spreading, cell migration, and cytoskeletal reorganization were also up-regulated in vitro and in vivo, such as CDC42, DNMBP, CAPG, NRAS, BCL9L, etc.." (PMID 39063079, 2024).
cancer (2 papers, 2021 to 2024). A tumor composed of atypical neoplastic, often pleomorphic cells that invade other tissues. "Interestingly, DNMBP is a guanine exchange factor (GEF) regulating CDC42, strengthening the hypothesis about an important role of EBV miRs in cancer." (PMID 39063079, 2024).
DNMBP also shares sentences with these, for which no sentence is quoted: infection (7 papers); Alzheimer disease (4); brain edema (2); Hypertension (2); adenoma (1); Anxiety (1); Atrophy (1); bacterial infection (1); Blindness (1); brain disorder (1); brain infarct (1); Cerebral ischemia (1); chronic kidney disease (1); corneal dystrophy (1); depression (1); Duchenne muscular dystrophy (1); endothelial dysfunction (1); female infertility (1); gastritis (1); glioma (1); H. pylori (1); Hyperglycemia (1); ischemia (1); ischemic stroke (1); major depressive disorder (1); neuroblastoma (1); progressive external ophthalmoplegia (1); retinal degeneration (1); retinitis pigmentosa (1); rheumatism (1).
A further 2 diseases each share a sentence with DNMBP in 1 paper.